S100B (S100 calcium binding protein B)
Diseases named in the same sentence as S100B in open-access papers (continued):
Sharing a sentence is not in itself a finding about the gene and the disease.
vitiligo (6 papers, 2021 to 2023). Generalized well circumscribed patches of leukoderma that are generally distributed over symmetric body locations and is due to autoimmune destruction of melanocytes. "Our study showed that S100B was only correlated with affected BSA in active vitiligo, but HMGB1 was associated with the vitiligo severity in both the active and stable stages." (PMID 36569840, 2022). "The findings demonstrated that although S100B was only correlated with the affected BSA in active vitiligo (r =0.60, P <0.001), HMGB1 was associated with the vitiligo severity in both the stable and active stages (stable phase, r=0.60, P <0.001; active phase, r=0.50, P <0.001)." (PMID 36569840, 2022). "In vitro studies using repeat freeze–thaw procedures identified intracellular S100B upregulation in normal and vitiligo melanocytes prior to its extensive release into the circulation." (PMID 36154894, 2022). "In general, increased S100B levels are closely related to vitiligo activity, but their precise molecular mechanisms require further exploration." (PMID 36154894, 2022). "We further note that S100B expression level was much higher in LCs of progressive vitiligo than in LCs from either stable vitiligo or healthy controls." (PMID 34207181, 2021). "Perhaps, on this final note, one can argue that the levels of S100B can be a predictive factor of the severity of conditions such as vitiligo." (PMID 33435332, 2021). "Multivariate logistic regression analysis showed S100B (OR, 1.019; 95% CI, 1.002-1.038; P =0.03), S100A9 (OR, 1.002; 95% CI, 1.001-1.003; P<0.001), and HMGB1 (OR, 1.915; 95% CI, 1.186-3.091; P =0.008) were significantly associated with vitiligo activity." (PMID 36569840, 2022). "Thus, we explored the association between S100B, S100A9, and HMGB1 and vitiligo severity in various disease activity phases." (PMID 36569840, 2022). "Among these alarmins, HMGB1 and S100B have been reported to be involved in the pathogenesis of vitiligo and could even serve as potential therapeutic targets for vitiligo." (PMID 36569840, 2022). "However, in the present study, we detected markedly higher S100B expression in LCs from progressive vitiligo than in LCs from healthy controls or stable vitiligo." (PMID 34207181, 2021). "Recently, S100B was also suggested as a potent biomarker of activity in progressive vitiligo." (PMID 34207181, 2021). "Furthermore, in a monobenzone-induced vitiligo mouse model, S100B inhibition was found to alleviate depigmentation in mouse skin." (PMID 34207181, 2021). "Our data suggest the possibility that S100B in LCs might also be involved in the activity or progression of vitiligo." (PMID 34207181, 2021). "In the current study, we aimed to address this question by analyzing LCs in skin sections from progressive and stable vitiligo, using confocal and immuno-electron microscopy to assess cell numbers and morphology, as well as expression of the vitiligo activity biomarker, S100B." (PMID 34207181, 2021). "Recently, S100B has also been suggested to act as a potent biomarker for vitiligo activity." (PMID 34207181, 2021). "In addition, we detected markedly increased S100B expression in the epidermis of skin from progressive vitiligo, and this was mainly observed in LCs." (PMID 34207181, 2021). "Moreover, S100B inhibitor pentamidine could stop hair graying in the monobenzone-induced depigmentation mice model, suggesting S100B as a potential therapeutic target for vitiligo." (PMID 36569840, 2022). "This phenomenon could explain increased S100B serum levels in the active phase of vitiligo." (PMID 36154894, 2022). "Additionally, expression of S100B, the activity biomarker of vitiligo, was increased in these LCs." (PMID 34207181, 2021). "Our ROC analysis revealed that serum IL-1α, S100B, S100A9, and HMGB1 had predictive capacity on the diagnosis of vitiligo." (PMID 36569840, 2022).
vitiligo (continued). "For vitiligo diagnosis, S100B had the highest sensitivity (92.31%), whereas HMGB1 had the highest specificity (85.71%); the combination of IL-1α, S100B, S100A9, and HMGB1 increased the AUC value to 0.925, with a sensitivity of 87.50% and a specificity of 85.71%." (PMID 36569840, 2022). "With the dual guarantee of multivariate logistic regression and ROC analysis, we found that serum HMGB1, S100B, and S100A9 can efficiently discriminate between patients with stable and active vitiligo, and can be used as potential biomarkers for the prediction of disease activity." (PMID 36569840, 2022). "Serum S100B levels, in patients with active non-segmental vitiligo, were significantly increased and correlated with affected body surface areas, suggesting its potential as a vitiligo biomarker." (PMID 36154894, 2022). "Therefore, in this study we would like to detect the serum expression of these alarmins (HMGB1, S100B, IL-1α, IL-33, S100A9, and S100A12) in NSV patients and healthy controls, to further investigate their clinical significance in the diagnosis and assessment of disease activity/severity in vitiligo." (PMID 36569840, 2022).
amyloid (5 papers, 2019 to 2025). "In a clinical sample, CSF S100B was specifically associated with amyloid and tau-deposition status." (PMID 35910248, 2022). "To investigate this, we analyzed S100B expression in animals aged 3, 7, and 10 months, representing pre-symptomatic, early amyloid deposition, and advanced disease stages, respectively." (PMID 40861781, 2025). "-Associated with amyloid plaques;-Present in diffuse (non-neuritic) amyloid deposits;-Overexpression of S100B ↑large plaques;-PSAPP/S100B-/-↓cortical amyloid plaque load and number;-S100B-positive astrocytes surround neuritic plaques." (PMID 31156365, 2019). "S100B surrounding amyloid plaques is mostly produced by astrocytes, but can also originate from oligodendrocytes and microglia." (PMID 31156365, 2019). "Our findings support that S100β might be involved in amyloid clearance from astrocytes, and due to the failure of transport, may lead to SP formation." (PMID 34209847, 2021). "In addition, some studies show that overexpression of astrocytic S100β is positively associated with the number of APP overexpressing neurons and in neurites with abnormal growth, suggesting that overexpression of S100β could be associated with amyloid plaque formation and AD progression in DS." (PMID 36212691, 2022).
astrocytoma (5 papers, 2004 to 2023). "Our results showed that control astrocytoma cell line exhibited overexpression of S100B after Aβ treatment, and subsequently cytotoxicity, increased ROS generation and NOS activation." (PMID 36982288, 2023). "Since yeast two-hybrid experiments have shown S100A6 to interact with S100B and co-localise in astrocytoma cells, we investigated the expression of both S100A6 and S100B in serial sections of prostatic adenocarcinoma of various Gleason scores and adjacent benign epithelium." (PMID 15280928, 2004). "Importantly, we observed that the tumor cells in the center zone displayed a prominent enrichment of stem cell markers Sox2 and Sox9, but did not express differentiated cell markers Olig2, CC1, S100β, and PDGFRα as observed in oligodendrocytoma and/or astrocytoma." (PMID 33863883, 2021).
atherosclerosis (5 papers, 2010 to 2022). A disease characterized by the build-up of fatty material and calcium deposition in the arterial wall resulting in partial or complete occlusion of the arterial lumen. "Taken together, the decreased level of S100B in cultured SMCs suggests its minimal involvement in atherosclerosis pathology; however, further investigations are warranted." (PMID 35531433, 2022). "Our results provide a potential strategy for the treatment of atherosclerosis by combating cell migration and asymmetric differentiation of a perivascular-derived S100β parent vSC population." (PMID 33649337, 2021). "Also, the major DAMPs including HMGB1 and S100B and their downstream signaling via TLR4 receptor have been intimately associated with the aggravated atherosclerosis resulting in the upregulation of proinflammatory cytokines including IL-18 and IL-1β." (PMID 35531433, 2022). "S100B stimulated inflammation and S100B receptor(siRAGE)may confer some cardiovascular benefits by modulating the inflammatory process in atherosclerosis." (PMID 33796567, 2020). "Since vascular SMC plays pivotal roles in the occurrence of diabetic complications such as atherosclerosis, we investigated the role of sRAGE in reducing the harmful effects of high-glucose (HG) or the RAGE ligands AGEs and S100B in cultured ASMC, and identified associated molecular mechanisms." (PMID 33182705, 2020). "Elucidation of this new cellular S100β source for generating SMC-like cells following injury expands our current understanding of vascular pathology and may represent an important therapeutic strategy for combating subclinical atherosclerosis." (PMID 33649337, 2021).
cerebrovascular disease (5 papers, 2017 to 2025). "We studied the relationship of NSE (biomarker of neuronal loss) and S100B (biomarker of glial destruction) with TCD parameters (index of cerebrovascular disease in patients with NTDT." (PMID 29244749, 2017). "Here we determined the changes of S100B, TRAIL, and adropin levels on atherothrombotic cerebrovascular disease." (PMID 35866730, 2022).
Crohn disease (5 papers, 2021 to 2025). A gastrointestinal disorder characterized by chronic inflammation involving all layers of the intestinal wall, noncaseating granulomas affecting the intestinal wall and regional lymph nodes, and transmural fibrosis. "For Crohn’s disease, the coefficient of determination (R2 = 0.780, p < 0.001) suggests a robust inverse association between dietary S100B levels and disease prevalence across countries." (PMID 40723919, 2025). "The analysis suggests that dietary patterns rich in S100B, such as Mediterranean and Italian diets, are correlated with higher alpha-diversity and lower estimated risk of inflammatory conditions such as Crohn’s disease." (PMID 40723919, 2025). "Furthermore, Western-style diets, with the lowest S100B levels, exhibited a higher relative risk for Crohn’s disease (R2 = 0.780)." (PMID 40723919, 2025). "Additionally, the relative risk of Crohn’s disease was assessed in different populations to examine potential links between dietary patterns, S100B, and chronic disease prevention." (PMID 40723919, 2025). "This study specifically aims to evaluate the estimated dietary intake of S100B across 13 global dietary patterns and to examine its association with microbiota alpha-diversity (Shannon index) and the relative risk of chronic diseases, including Crohn’s disease." (PMID 40723919, 2025). "For these reasons, Crohn’s disease represents a biologically plausible model to explore how dietary S100B intake could influence microbiota-driven inflammation." (PMID 40723919, 2025). "Activation of the S100B–RAGE axis has been associated with either pro- or anti-inflammatory responses depending on the context and concentration, and may represent a plausible mechanism linking dietary S100B intake with modulation of gut inflammation, including in Crohn’s disease." (PMID 40723919, 2025).
encephalitis (5 papers, 2009 to 2022). An acute inflammatory process affecting the brain parenchyma. "For example, CSF S100B levels over 960 pg/mL were associated with higher risk of brain injury in encephalitis of viral, bacterial, and unknown etiology." (PMID 31093802, 2019). "Furthermore, too much reliance on non-specific markers of degeneration in CSF such as 14.3.3 and S100B proteins, positive in both tested encephalitis patients, can result in an incorrect diagnosis." (PMID 25246643, 2015).
hemorrhage (5 papers, 2011 to 2021). Loss of blood from the vascular compartment to the exterior or into nonvascular body space as a result of rupture or severance of the blood vessels. "In the absence of an early biomarker to identify patients who will remain unconscious (i.e., with severe EBI) 3 days after the bleeding, we hypothesized that early S100B serum concentration reflects the extent of EBI caused by the primary hemorrhage." (PMID 32516898, 2020). "All 7 of the neuronal protein markers along with S100β rose in a subset of aSAH patients during the post-hemorrhage period, and their levels varied markedly over time and across patients." (PMID 22174930, 2011). "Furthermore, we could not separately analyze patients with early complications, such as re-bleeding, in whom the S100B levels did not only reflect brain injury due to the primary hemorrhage." (PMID 32516898, 2020). "ACTH1-24 dampened the deleterious effects of collagenase-induced hemorrhage in significantly reducing the extension of the damaged area, the striatal neuronal and glial losses, and the immunoreactive expression of the GFAP, S100β, and NG2-glia biomarkers in the affected periventricular area." (PMID 33082383, 2020).
Lupus (5 papers, 2010 to 2023). "Although lesser ODs were detected for ANA, TG2, TG6, heparin, α-myosin, chondroitin sulfate, Lupus RO-60, fibrinogen, tyrosinase, β catenin, thyroid peroxidase, claudin 7, sulfatides, somatotropin, S100B, somatostatin and actin, their p values were still very, very significant." (PMID 37845267, 2023). "Among subjects with systemic lupus erythematosus, concentrations of S100B were elevated (relative to controls) among subjects without central nervous system involvement, although to a lesser extent than among subjects with neurologic or psychiatric manifestations." (PMID 21034449, 2010).
memory impairment (5 papers, 2014 to 2025). "It has been reported that the overexpression of S100 in the mouse brain causes memory impairment, and increased release of S100B from astrocytes may be involved in the memory impairment seen in the early stages of Alzheimer’s disease." (PMID 35437315, 2022). "In addition, patients with deficit syndrome present higher S100B serum and elevated serum S100B levels have linked to memory impairment." (PMID 25202915, 2014). "Furthermore, persistently high S100B concentrations correlate with memory impairment in patients with chronic SCZ." (PMID 30618856, 2018).
schwannoma (5 papers, 2014 to 2024). A benign, usually encapsulated slow growing tumor composed of Schwann cells. "Some studies point to an association between SOX10 and S100B; for instance, knockdown of SOX10 in Schwannoma cells drastically reduces S100B levels." (PMID 25536222, 2014). "MMP9 was strongly colocalized with CD31/PECAM1 + endothelial cells and S100B + schwannoma cells." (PMID 38887507, 2024). "The expression of Schwann cell differentiation markers S100B and SOX10 was used to identify 7 clusters of schwannoma cells and 6 clusters of microenvironment cells." (PMID 38216587, 2024). "A predominantly cytoplasmic immunostaining for S100β (using antibodies from Sigma and Abcam) was observed in HDF-a, similar to the immunostaining pattern observed in the rat schwannoma cell line." (PMID 26678612, 2015).
Sleep apnea (5 papers, 2017 to 2025). An intermittent cessation of airflow at the mouth and nose during sleep is known as sleep apnea. "It is known that elevated levels of S100B, a dimeric calcium-binding protein in brain astrocytes, has been associated with conditions of hypoxia, such as high altitude and obstructive sleep apnoea." (PMID 29287596, 2017). "The present investigation is unique in its comprehensive analysis of IL-6, IL-8, IL-10, TNF-α, CRP, and S100B in a single cohort of sleep apnea patients compared to non-OSA controls in both serum and plasma." (PMID 37762178, 2023).
status epilepticus (5 papers, 2014 to 2023). Status epilepticus is defined as a continuous seizure lasting more than 30 min, or two or more seizures without full recovery of consciousness between any of them. "Associations between S100B and candidate genes for dyslexia have been reported; in patients suffering from status epilepticus, significantly-increased levels of S100B were found in comparison with controls or patients with pharmacoresistant epilepsy." (PMID 36771418, 2023). "Regarding status epilepticus, increased levels of S100B in the CSF have been found in a lithium–pilocarpine rat model of SE, which correlated with evidence of neurodegeneration in the dentate gyrus and CA1 hippocampal subfield and an increase in mossy fiber sprouting 24 h after SE induction." (PMID 37569895, 2023). "Uptake of labeled S100B by rat spleen CD4+ or CD8+ and CD86+ dendritic cells was exacerbated by pilocarpine-induced status epilepticus which is accompanied by BBBD." (PMID 24988410, 2014). "While P2Y1 was detectable at low levels in cortical neurons and microglia under control conditions and following status epilepticus, no co-localization was observed using the astrocyte markers GFAP and S100β in vehicle-injected control mice and in mice subjected to status epilepticus." (PMID 32009961, 2019).
attention deficit-hyperactivity disorder (4 papers, 2010 to 2023). A disorder characterized by a marked pattern of inattention and/or hyperactivity-impulsivity that is inconsistent with developmental level and clearly interferes with functioning in at least two settings (e.g. at home and at school). "Only five reports concern S100B levels in Attention Deficit-Hyperactivity Disorder (ADHD), and three of them are performed on the same study group: 35 children diagnosed with ADHD, including 21 medication-naïve and 14 medicated patients." (PMID 37759935, 2023).
cerebral small vessel disease (4 papers, 2017 to 2025). Cerebral small vessel disease is the term currently used to pathological processes that affect the brain parenchymal circulation (arterioles, capillaries, and veins). "Elevated blood-based S100B levels have also been observed among individuals with AD and cerebral small vessel disease (cSVD)." (PMID 39907937, 2025).
chorioamnionitis (4 papers, 2013 to 2023). A morphologic finding indicating inflammation of the fetal sac membranes. "In the same light, s100b protein levels were positively associated with chorioamnionitis similar to sRAGE protein levels." (PMID 24324804, 2013).
chronic heart failure (4 papers, 2020 to 2024). "In conclusion, our study demonstrates that elevated serum S100B levels in chronic heart failure (HF) patients are associated with both cardiac and cognitive dysfunction." (PMID 39201780, 2024). "In this study, we investigated the serum levels of S100B in 146 patients with chronic heart failure (HF) and their association with cardiac and cognitive dysfunction." (PMID 39201780, 2024). "Recently, Chen (2020) reported that plasma miR-340-3p and S100B levels differ significantly among various rs9722 genotypes and that the S100B rs9722 locus SNP is associated with the risk of chronic heart failure." (PMID 33982673, 2021). "Additionally, single nucleotide polymorphism (SNP) of S100B rs9722 is associated with the risk of chronic heart failure in the Chinese Han population." (PMID 37217870, 2023). "Recent research has expanded the understanding of S100B, uncovering its significant role in the pathogenesis of cardiovascular diseases, including chronic heart failure (HF)." (PMID 39201780, 2024). "The level of S100B in patients with chronic heart failure is significantly increased and significantly correlates with left ventricular ejection fraction, left ventricular end-diastolic volume, and NT-proBNP." (PMID 37217870, 2023). "S100B has also been found to be an independent prognosis factor in chronic heart failure and major cardiac events." (PMID 33172087, 2020).